DUXAP8 (double homeobox A pseudogene 8)
Gene: Transcribed processed pseudogene on chromosome 22 (15,826,566 to 15,827,187, forward strand). Ensembl gene ENSG00000271672.
Diseases named in the same sentence as DUXAP8 in open-access papers:
DUXAP8 is named in the same sentence as 41 diseases in open-access papers, as found by Europe PMC text mining. Sharing a sentence is not in itself a finding about the gene and the disease. The quoted sentences say what the papers report.
gastric cancer (15 papers, 2017 to 2022). A primary or metastatic malignant neoplasm involving the stomach. "It has been shown that DUXAP8 can significantly inhibit the expression of PLEKHO1 in gastric cancer, enhancing the proliferation and migration of tumor cells." (PMID 34957112, 2021). "DUXAP8 can significantly inhibit the expression of PLEKHO1 in gastric cancer, which enhances the proliferation and migration of tumor cells." (PMID 34957112, 2021). "As shown in the previous study, lncRNA DUXAP8 was found to promote gastric cancer (GC) progression and development." (PMID 33522355, 2021). "DUXAP8, as a newly-found lncRNA, has been unveiled to possess oncogenic potential in gastric cancer." (PMID 34774078, 2021). "Increased DUXAP8 expression has also been detected in gastric cancer tissues compared to corresponding normal tissues." (PMID 34631702, 2021). "In the past two years, studies have reported that lncRNA DUXAP8 promoted the proliferation and invasion of renal cell carcinoma, esophageal squamous cell carcinoma, gastric cancer, non-small cell lung cancer, and other tumors." (PMID 33522355, 2021). "DUXAP8, a 2107 bp RNA, was initially found to be overexpressed in gastric cancer (GC) tissues, its overexpression resulted in larger tumor size, advanced tumor stage, lymphatic metastasis, and poor prognosis of GC patients." (PMID 32922554, 2020). "Several studies suggest that LncRNAs DUXAP8 regulate cell proliferation and migration in several cancers, such as bladder cancer, gastric cancer, and esophageal squamous cell cancer." (PMID 33817152, 2019). "DUXAP8 has been reported to function as an oncogene in glioma, pancreatic cancer, bladder cancer, gastric cancer, non-small-cell lung cancer as well as renal cell carcinoma." (PMID 31409759, 2019). "In gastric cancer, DUXAP8 could promote tumor growth by interacting with the PRC2 complex to inhibit PLEKHO1 expression." (PMID 32849765, 2020). "Additionally, the Double Homeobox A Pseudogene 8 (DUXAP8) expressed-lncRNA, enhances gastric cancer cell proliferation and tumorigenesis through silencing PLEKHO1 transcription epigenetically, by binding to EZH2 and SUZ12." (PMID 30018188, 2018). "In this review, we comprehensively summarize existing research on DUXAP8 functional roles in various cancers, such as bladder cancer, HCC, CRC, RCC, NSCLC, esophageal cancer, oral cancer, gastric cancer, neuroblastoma, thyroid carcinoma, and breast cancer." (PMID 34631702, 2021). "Double homeobox A pseudogene 8 expression was upregulated in various cancers, such as bladder cancer, hepatocellular carcinoma (HCC), colorectal cancer (CRC), lung cancers, oral cancers, gastric cancer, ovarian cancer, pancreatic cancer, neuroblastoma, and pancreatic cancer." (PMID 34631702, 2021). "Moreover, DUXAP8 was also found to be over-expressed in human gastric cancer, and increased DUXAP8 promoted cells proliferation and invasion through epigenetically silencing PLEKHO1 expression by binding with EZH2 and SUZ12 in gastric cancer cells." (PMID 29152119, 2017).
pancreatic cancer (15 papers, 2018 to 2023). "DUXAP8 upregulation was also associated with larger tumor size, advanced pathologic stage and shorter OS of pancreatic cancer patients." (PMID 30367681, 2018). "Here, we aimed to identify the association between pseudogene derived lncRNA DUXAP8 and growth of pancreatic cancer cells." (PMID 30367681, 2018). "RNA immunoprecipitation, chromosome immunoprecipitation assay and rescue experiments were performed to analyze the association of DUXAP8 with target proteins and genes in pancreatic cancer cells." (PMID 30367681, 2018). "High DUXAP8 expression was associated with a larger tumor size, advanced pathological stage and shorter overall survival of pancreatic cancer patients." (PMID 30367681, 2018). "In the current study, we sought to investigate the association between DUXAP8 expression and OS of pancreatic cancer patients and further delineate the effects of DUXAP8 on the growth of pancreatic cancer cells both in vitro and in vivo and the underlying mechanism." (PMID 30367681, 2018). "There was significant DUXAP8 up regulation in pancreatic cancer tissues that was correlated with the larger size of the tumor, advanced clinical stage, and shorter survival rate." (PMID 37807067, 2023). "DUXAP8 promoted the cell proliferation and tumor progression in pancreatic cancer through p21 and KLF2 down regulations following interaction with EZH2 and LSD1." (PMID 37807067, 2023). "By downregulating DUXAP8 in lung cancer cells, it is not only possible to inhibit the proliferation of pancreatic cancer cells through silencing CDKN1A and KLF2, but also to induce their apoptosis." (PMID 34431643, 2021). "In pancreatic carcinoma, DUXAP8 promotes tumor growth through epigenetically silencing CDKN1A and KLF2." (PMID 34957112, 2021). "By epigenetically silencing CDKN1A an KLF2, DUXAP8, upregulated in pancreatic cancer, promoted growth of pancreatic cancer." (PMID 32185172, 2020). "In pancreatic cancer, DUXAP8 enhanced cancer cell proliferation by epigenetically silencing CDKN1A and KLF2." (PMID 32849765, 2020). "Loss-of-function approaches were used to investigate the potential functional roles of DUXAP8 in pancreatic cancer cell proliferation and apoptosis in vitro and in vivo." (PMID 30367681, 2018). "Our results suggest that tumor expression of pseudogene derived lncRNA DUXAP8 plays an important role in pancreatic cancer progression." (PMID 30367681, 2018). "To investigate the biological function of DUXAP8 in pancreatic cancer cells, we first evaluated DUXAP8 expression in pancreatic cancer cells by qRT-PCR assays." (PMID 30367681, 2018). "To investigate the molecular mechanism of DUXAP8 in pancreatic cancer cells, we examined the effects of DUXAP8 knockdown on a total of 9 different cell proliferation related transcripts in BxPC-3 and PANC-1 cells." (PMID 30367681, 2018). "Pancreatic cancer tissues had significantly higher DUXAP8 levels than paired adjacent normal tissues." (PMID 30367681, 2018). "Subsequently, considering the expression level of candidate lncRNAs in pancreatic cancer, we focused on the pseudogene derived lncRNA DUXAP8 for subsequent study." (PMID 30367681, 2018). "In this study, we identified the pseudogene derived lncRNA DUXAP8 as a novel modulator of pancreatic cancer progression." (PMID 30367681, 2018). "Quantitative real-time reverse transcription polymerase chain reaction was used to assess the relative expression of DUXAP8 in pancreatic cancer tissues and cells." (PMID 30367681, 2018). "Consistently with these circumstantial findings, knockdown of DUXAP8 remarkably inhibited pancreatic cancer cell proliferation, induced apoptosis, and promoted cell cycle arrest." (PMID 30367681, 2018). "DUXAP8 promoted pancreatic cancer cell growth by epigenetically regulating CDKN1A and KLF2." (PMID 35794983, 2022). "In pancreatic cancer, lncRNA DUXAP8 competitively binds miR-448 to upregulate WTAP expression." (PMID 36139062, 2022).
pancreatic cancer (continued). "Next, to further investigate whether CDKN1A and KLF2 are involved in the enhanced cellular proliferation induced by DUXAP8 in pancreatic cancer cells, we performed rescue experiments." (PMID 30367681, 2018). "Our finding indicated that DUXAP8 may serve as a potential therapeutic target for intervention against pancreatic cancer." (PMID 30367681, 2018). "MTT assays confirmed that knockdown of DUXAP8 suppressed the growth of pancreatic cancer cells." (PMID 30367681, 2018). "DUXAP8 induced increase in pancreatic cancer cell proliferation and tumorigenesis may be partly mediated via epigenetically silencing CDKN1A and KLF2 transcription by binding with EZH2 and LSD1." (PMID 30367681, 2018). "In summary, we reported a crucial tumor-promoting pseudogene derived lncRNA DUXAP8 in pancreatic cancer, which may serve as a new therapeutic target for pancreatic cancer." (PMID 30367681, 2018). "Moreover, silencing DUXAP8 expression by siRNA or shRNA inhibited pancreatic cancer cell proliferation and promoted apoptosis in vitro and in vivo." (PMID 30367681, 2018). "This study provides the first direct evidence that DUXAP8 is a critical and powerful regulator of genes involved in pancreatic cancer progression through silencing CDKN1A and KLF2 in the nucleus, indicating that DUXAP8 is a potential therapeutic target of pancreatic cancer." (PMID 30367681, 2018). "DUXAP8 may serve as a candidate biomarker and represent a novel therapeutic target of pancreatic cancer." (PMID 30367681, 2018). "Similarly, DUXAP8 was up-regulated in pancreatic cancer tissues." (PMID 32922554, 2020). "Importantly, DUXAP8 was significantly upregulated in pancreatic cancer tissues and cells." (PMID 30367681, 2018). "LncRNA DUXAP8 can regulate the Fak signaling pathway through miR-448/WTAP axis to promote migration and invasion of pancreatic cancer cells." (PMID 36139062, 2022). "Double homeobox A pseudogene 8 (DUXAP8), a pseudogene‐derived lncRNA, may play a promoting role in pancreatic cancer, non‐small‐cell lung cancer, and HCC through actions on the Fork head Box M1 (FoxM1) protein." (PMID 37337470, 2023). "Double homeobox A pseudogene 8 (DUXAP8), a novel lncRNA, has been reported to be involved in many cancers, including gastric, colorectal, esophageal, bladder, oral, ovarian, lung, and pancreatic cancers as well as hepatocellular carcinoma (HCC)." (PMID 34631702, 2021). "DUXAP8 could be sponged by various microRNAs, such as miR-20b-5p, miR-584-5p, or miR-448, to play a role in proliferation of papillary thyroid carcinoma cells, HCC, and pancreatic carcinoma." (PMID 36246594, 2022). "However, the clinical significance and functional role of DUXAP8 expression in pancreatic cancer has not been reported yet." (PMID 30367681, 2018).
renal cell carcinoma (14 papers, 2018 to 2025). "Another study reported that DUXAP8 downregulates miR-126 expression, which, in turn, promotes the renal cell carcinoma progression." (PMID 35287542, 2022). "For instance, a report showed that miR-126 was down-regulated by lncRNA DUXAP8 to enhance renal cell carcinoma progression." (PMID 33522355, 2021). "Studies have shown that DUXAP8 facilitated cell growth in renal cell carcinoma and served as a promising biomarker in this disease." (PMID 34774078, 2021). "Pseudogene DUXAP8 is a novel lncRNA that has been reported to be overexpressed in a series of human cancers, including glioma and renal cell carcinoma." (PMID 32849765, 2020). "LncRNA DUXAP8 enhances renal cell carcinoma progression by negatively regulating miR-126." (PMID 40764609, 2025). "DUXAP8 was also discovered to enhance progression of renal cell carcinoma." (PMID 32185172, 2020). "This suggested that DUXAP8 is up-regulated and increases metastasis of renal cell carcinoma cells." (PMID 32922554, 2020). "Moreover, functional experiments demonstrated that knockdown of pseudogenes DUXAP8/DUXAP9 reduced proliferative ability of renal cell carcinoma." (PMID 31409759, 2019). "Recent studies have reported that DUXAP8 mRNA is substantially upregulated in many cancer tissues, including pancreatic, bladder, colon, lung, ovarian, and breast cancers, as well as thyroid, hepatocellular and renal cell carcinomas (RCCs), and glioma, compared to corresponding non-tumor tissues." (PMID 34631702, 2021). "Functional experiments showed that DUXAP8 and DUXAP9 enhanced but miR-29c-3p weakened growth of renal cell carcinoma." (PMID 31409759, 2019). "Firstly, we determined the expression levels of five constituents (DUXAP8, DUXAP9, miR-29c-3p, COL1A1 and COL1A2) in 20 pairs of clinical cancer tissues and normal tissues of renal cell carcinoma." (PMID 31409759, 2019). "These bioinformatic analytic findings indicate that pseudogene DUXAP8 and DUXAP9 may fuel onset and development of renal cell carcinoma by targeting COL1A1 and COL1A2 through competitively binding miR-29c-3p." (PMID 31409759, 2019). "Taken together, miR-29c-3p may be a potential binding miRNA of DUXAP8 and DUXAP9 in renal cell carcinoma." (PMID 31409759, 2019). "Finally, we detected proliferative roles of DUXAP8, DUXAP9 and miR-29c-3p in renal cell carcinoma cell lines." (PMID 31409759, 2019). "All these findings suggest that pseudogene DUXAP8/DUXAP9-miR-29c-3p-COL1A1/COL1A2 may be a critical signaling pathway in onset and progression of renal cell carcinoma." (PMID 31409759, 2019). "Our current results indicated that DUXAP8 and DUXAP9 may act as two key oncogenes in renal cell carcinoma through upregulation of COL1A1 and COL1A2 by competitively binding miR-29c-3p." (PMID 31409759, 2019). "The oncogenic function of CXCR4 exhibits tissue-specific regulation: while DUXAP8 lncRNA upregulates CXCR4 via miR-223 sequestration in papillary thyroid carcinoma, miR-1246-mediated CXCR4 suppression attenuates proliferative and migratory capacities in renal cell carcinoma." (PMID 40396123, 2025). "Taken together, amplification of pseudogenes DUXAP8 and DUXAP9 may lead to increase expression of COL1A1 and COL1A2 by competitively binding to miR-29c-3p, resulting in uncontrolled cell proliferation in renal cell carcinoma." (PMID 31409759, 2019).
hepatocellular carcinoma (13 papers, 2020 to 2026). A malignant tumor that arises from hepatocytes. "DUXAP8 serves as a sponge of MiR-490-5p to promote the expression of BUB1 in hepatocellular carcinoma." (PMID 36787437, 2023). "For example, DUXAP8 promotes the progression of hepatocellular carcinoma by sponging miR-422a and enhancing PDK2 expression." (PMID 34774078, 2021). "Double homeobox A pseudogene 8 (DUXAP8), derived from a pseudogene, is highly expressed in many cancers, such as hepatocellular carcinoma, colorectal cancer and oral cancer." (PMID 34235076, 2021).
non-small cell lung carcinoma (12 papers, 2017 to 2021). A group of at least three distinct histological types of lung cancer, including non-small cell squamous cell carcinoma, adenocarcinoma, and large cell carcinoma. "Research in non-small-cell lung cancer indicated that lncRNA DUXAP8, linked with miR-409-3p, exerted the role of promoting cell migration and glycolysis through up-regulating the expression of HK2 and LDHA." (PMID 33522355, 2021). "Our study suggests that increased overexpression of pseudogene-derived LncRNA DUXAP8 is one of the important causes of non-small cell lung cancer." (PMID 33817152, 2019). "Another study sheds light on the critical role of DUXAP8 in regulating the proliferation and invasion of non-small-cell lung cancer cells." (PMID 33522355, 2021). "DUXAP8 was initially reported to promote non-small-cell lung cancer proliferation and invasion by epigenetically silencing EGR1 and RHOB." (PMID 32849765, 2020). "Taken together, our results imply that LncRNA DUXAP8 is a potential regulatory molecular marker in non-small-cell lung cancer." (PMID 33817152, 2019). "To determine the relationship between LncRNA DUXAP8 and non-small-cell lung cancer, we examined the expression of LncRNA DUXAP8 in lung cancer tissues and cells." (PMID 33817152, 2019). "In this study, we examine the expression of LncRNA DUXAP8 in non-small-cell lung cancer and cells and further analyze its relationship to cell proliferation and invasion." (PMID 33817152, 2019). "Recent studies indicated that DUXAP8 has a critical role in non-small-cell lung cancer cell proliferation and invasion by epigenetically silencing EGR1 and RHOB." (PMID 30367681, 2018). "DUXAP8 is a transcribed pseudogene that upregulated in non-small-cell lung cancer tissues and exhibited poor OS." (PMID 29291003, 2017). "The pseudogene DUXAP8 may act as an oncogene in non-small cell lung cancer, and it may play this role by silencing EGR1 and RHOB transcription via binding with EZH2 and LSD1." (PMID 33711952, 2021). "Recently, Sun and colleagues found that DUXAP8 is significantly up-regulated in human non small cell lung cancer tissues, and knockdown of DUXAP8 expression could inhibits NSCLC cells proliferation, migration, invasion and induces apoptosis in vitro." (PMID 29152119, 2017). "In non-small cell lung cancer (NSCLC), DUXAP8 promotes tumor cell proliferation and invasion through epigenetically silencing Egr1 and RHOB." (PMID 34957112, 2021). "In non-small cell lung cancer (NSCLC), DUXAP8 promotes tumor cell proliferation and invasion through epigenetic silencing of Egr1 and RHOB." (PMID 34957112, 2021).
bladder cancer (9 papers, 2019 to 2022). "Similar to Liu’s research, DUXAP8 might be a useful lncRNAs resource for prognostic or diagnostic markers for bladder cancer." (PMID 35280814, 2022). "Advanced stage bladder cancer patients frequently have higher DUXAP8 mRNA expression levels than stage I and stage II patients." (PMID 34631702, 2021). "Previous studies have revealed that DUXAP8 promotes bladder cancer cell proliferation by regulating PTEN." (PMID 34431643, 2021). "Researchers have detected substantially elevated lncRNA DUXAP8 expression in bladder cancer tissues compared with adjacent normal tissues." (PMID 34631702, 2021). "DUXAP8 is differentially expressed in bladder cancer, its downregulation inhibits cell invasion and proliferation and leads to cell apoptosis." (PMID 32922554, 2020). "DUXAP8 can regulate PTEN to alter the prognosis of bladder cancer." (PMID 35280814, 2022). "Comprehensive profiling analysis revealed that DUXAP8 is upregulated in Bladder Cancer (BC)." (PMID 32922554, 2020). "In bladder cancer, knockdown of DUXAP8 inhibited tumor proliferation through PTEN." (PMID 32849765, 2020). "Previous studies have identified that lncRNAs like LINC00460, UCA1, LINC00958, LINC01296, SNH12, and DUXAP8 are implicated in bladder cancer, but did not examine the entire landscape of lncRNA transcripts." (PMID 31810243, 2019). "DUXAP8 is a novel lncRNAs and has been revealed to be upregulated in multiple human cancers, including HCC, bladder cancer, and esophageal squamous cell cancer." (PMID 32849765, 2020).
colorectal cancer (8 papers, 2020 to 2022). A primary or metastatic malignant neoplasm that affects the colon or rectum. "DUXAP8 was remarkably overexpressed in colorectal cancer and DUXAP8 knockdown led to inhibited proliferation, migration and invasion and enhanced apoptosis." (PMID 32185172, 2020). "DUXAP8, upregulated by STAT3, also fueled migration and invasion of colorectal cancer by functioning as a ceRNA for miR-577 to regulate RAB14." (PMID 32185172, 2020). "A positive DUXAP8/miR‐577/RAB14 feedback loop promotes cell migration and invasion in colorectal cancer." (PMID 32248648, 2020).
glioma (6 papers, 2019 to 2022). A benign or malignant brain and spinal cord tumor that arises from glial cells (astrocytes, oligodendrocytes, ependymal cells). "For instance, DUXAP8 is up-regulated in glioma cells, and knockdown of DUXAP8 suppresses the proliferation of glioma." (PMID 34819492, 2021). "In glioma, the downregulation of DUXAP8 inhibits the proliferation of tumor cells." (PMID 34957112, 2021). "In glioma, downregulation of DUXAP8 inhibits the proliferation of tumor cells." (PMID 34957112, 2021).
lung cancer (6 papers, 2019 to 2022). A malignant neoplasm involving the lung. "Our results demonstrated that EGR1 is upregulated in response to knockdown of DUXAP8, inhibiting lung cancer growth." (PMID 34235076, 2021). "Among 4 lung cancer cell lines, LncRNA DUXAP8 in A549 cells was the highest (P<0.001)." (PMID 33817152, 2019). "Compared with normal lung tissue, LncRNA DUXAP8 was significantly up-regulated in NSCLC, especially in stage III / IV and diameter ≥ 3cm of lung cancer." (PMID 33817152, 2019).